UCN (urocortin)
Description:
Hormone that plays a central role in whole body adaptation to stress. Released by the hypothalamus primarily in response to physical or psychological stress and acts by binding to CRH receptors CRHR1 and CRHR2. UCN-dependent signaling is a primary mediator of the neuroendocrine, autonomic (fight-or-flight) and behavioral responses to stress, acting as a key regulator of adaptation by activating the hypothalamus-pituitary-adrenal axis, leading to corticotropin hormone (ACTH) production. Plays a role in the establishment of normal hearing thresholds (By similarity). Reduces food intake and regulates ghrelin levels in gastric body and plasma (By similarity).
Synonyms: UROC; UI; UCN1
Tractability: Small molecule: a structure with a bound ligand is known. Antibody: its Gene Ontology location is reachable by antibodies, with high confidence; UniProt places it where antibodies can reach, with medium confidence; UniProt predicts a signal peptide or a membrane-spanning region; the Human Protein Atlas places it where antibodies can reach.
Gene: Protein-coding gene on chromosome 2 (27,307,400 to 27,308,445, reverse strand). Ensembl gene ENSG00000163794.
Subcellular location: Secreted
Subcellular location (Human Protein Atlas): Vesicles; Plasma membrane; Predicted to be secreted
Pathways (Reactome):
Metabolism of proteins: Synthesis, secretion, and deacylation of Ghrelin
Signal Transduction: Class B/2 (Secretin family receptors)
Gene Ontology:
Molecular function: corticotropin-releasing hormone activity; protein binding; corticotropin-releasing hormone receptor 1 binding; corticotropin-releasing hormone receptor 2 binding; histone deacetylase inhibitor activity; neuropeptide hormone activity; G protein-coupled receptor binding; hormone activity
Biological process: positive regulation of corticotropin secretion; G protein-coupled receptor signaling pathway; general adaptation syndrome; negative regulation of appetite; neuropeptide signaling pathway; aerobic respiration; associative learning; drinking behavior; feeding behavior; female pregnancy; learning or memory; negative regulation of apoptotic process; negative regulation of blood pressure; negative regulation of cell size; negative regulation of feeding behavior; negative regulation of gene expression; negative regulation of hormone secretion; negative regulation of neuron apoptotic process; neuron projection development; positive regulation of behavioral fear response; positive regulation of calcium ion import; positive regulation of cAMP/PKA signal transduction; positive regulation of cardiac muscle contraction; positive regulation of cell growth; positive regulation of collagen biosynthetic process; and 15 more
Cellular component: extracellular region; neuronal cell body; axon; axon terminus; dendrite; perikaryon; varicosity
Genetic constraint (gnomAD): Loss-of-function variants: 5 observed, 5.08 expected, observed/expected ratio (o/e) 0.98, 90% interval 0.5 to 1.8. That is too few expected variants to judge how well the gene tolerates losing a copy. Missense variants: 195 observed, 170.19 expected, observed/expected ratio (o/e) 1.15, 90% interval 1.02 to 1.29. Synonymous variants: 95 observed, 89 expected, observed/expected ratio (o/e) 1.07, 90% interval 0.9 to 1.27.
Homologues: Orthologues: chimpanzee UCN (98% identical), macaque UCN (94% identical), dog UCN (87% identical), rabbit UCN (87% identical), pig UCN (85% identical), mouse Ucn (81% identical), rat Ucn (81% identical), tropical clawed frog ucn (35% identical), zebrafish uts1 (32% identical). Paralogues in human: CRH (34% identical).
Diseases named in the same sentence as UCN in open-access papers:
UCN is named in the same sentence as 78 diseases in open-access papers, as found by Europe PMC text mining. Sharing a sentence is not in itself a finding about the gene and the disease. The quoted sentences say what the papers report.
Anxiety (14 papers, 2012 to 2025). Intense feelings of nervousness, tension, or panic often arise in response to interpersonal stresses. "It has been indicated that the LDT contains CRF- and urocortin (Ucn1)-containing neurons, which are involved in the stress-associated progression of anxiety, depression, SUD, inappropriate arousal, and control of the sleep and wakefulness." (PMID 37045899, 2023). "This increase in anxiety in triple urocortin knockout mice was also associated with serotonergic function in stress-linked neurocircuits." (PMID 23487366, 2013). "In this work we aimed at investigating whether neuron loss and alpha-synuclein accumulation in the urocortin 1 containing (UCN1) cells of the centrally-projecting Edinger–Westphal (EWcp) nucleus is associated with anxiety and depression-like state in the rat." (PMID 35109869, 2022). "Isoforms of CRF receptor are known to mediate the effects of urocortin stress ligands on the regulation of stress responses, anxiety, and feeding behavior; however, urocortin stress ligands also influence cell proliferation." (PMID 36971048, 2023). "A double KO of UCN 1 and 2, however, results in a anxiolytic-like phenotype while UCN triple KO mice show normal basal anxiety levels but increased anxiety-like behavior 24 h after a stressor." (PMID 24065880, 2013). "Remarkably, the triple urocortin knockout mouse showed an increase in anxiety-like behavior 24 h post-stress." (PMID 23487366, 2013). "Excessive stress may produce a pathological stimulation of the CRF/CRF1 system in the cerebral cortex and amygdala, which overrules the urocortin/CRF2 system in the LS and hippocampus, leading to stress-related diseases, such as anxiety and depression." (PMID 37626714, 2023). "However, the ICV administration of Ucn1, Ucn2, and Ucn3 in mice, and the global knock-out of urocortins and their receptors led to different results regarding the activation of the HPA-axis, as well as for anxiety- and depression-like behavior." (PMID 37626714, 2023). "However, given that both CRF and UCN's can activate CRF2 receptors, it is not surprising that there is not a noticeable change in anxiety or consistent decrease in depression-like behaviors in the UCN 2 or 3 KO mice." (PMID 24065880, 2013).
endometriosis (14 papers, 2012 to 2025). The growth of functional endometrial tissue in anatomic sites outside the uterine body. "To date, few studies have evaluated the use of urocortin as a diagnostic marker of endometriosis." (PMID 34201813, 2021). "Our results indicated a minimal variability of serum Urocortin with comparable levels between ovarian endometriosis, parietal endometriosis, and control groups." (PMID 41011062, 2025). "The study investigated serum and urinary levels of Urocortin and Histone H4 in patients with ovarian and parietal endometriosis compared to healthy controls, using a multidimensional approach encompassing several clinico-pathological parameters." (PMID 41011062, 2025). "Urinary Urocortin levels showed heterogeneity, with significantly higher values in the ovarian endometriosis group compared to the parietal endometriosis and control group (p = 0.001)." (PMID 41011062, 2025). "Urocortin (UCN, Uniprot: P55089) is a neuropeptide present in the endometrium and ovaries, with research indicating similar serum levels in individuals with endometriosis and healthy controls." (PMID 41009445, 2025). "UCN has been shown to be upregulated in endometriosis, down-regulated in endometrial carcinoma; whereas, it is reported as present in prostate, renal and gastric adenocarcinoma." (PMID 37382757, 2024). "According to some studies, evaluating the plasma urocortin levels enables detection of symptomatic endometriosis with a high sensitivity (76–88%) and specificity (88–90%)." (PMID 34201813, 2021). "Nevertheless, not all of the reported scientific studies confirm the usefulness of urocortin as a marker of symptomatic endometriosis." (PMID 34201813, 2021). "Elevated urocortin levels were indicative of endometriosis with 88% sensitivity and 90% specificity, while CA-125 was able to detect only 65% of the cases with the same specificity." (PMID 34201813, 2021). "The apparent finding of increased UCN-1 plasma levels improves the prospects for diagnosis of endometriosis in symptomatic patients." (PMID 33946650, 2021). "In women suffering from endometriosis, theexpression of UCN, UCN2 and UCN3 transcripts wasthe same in the secretory and the proliferative phases,whereas in healthy women UCN levels differed betweenthe two phases." (PMID 30644237, 2019). "The expression and function of CRH and UCN have also been found to be impaired in eutopic endometrium of women with endometriosis." (PMID 23638035, 2013). "CA 125, Ca 19.9, ICAM-1, and IL-6 together with follistatin and urocortin have proven to be the most reliable markers for endometriosis diagnosis." (PMID 23093966, 2012). "However, there is a great variability in the accuracy of Urocortin as a valuable biomarker in endometriosis, mainly due to methodological approaches, with reported sensitivity of 76.2%, 80%, 88% and specificity of 45.7%, 90%." (PMID 41011062, 2025). "Therefore, our study focusing on Urocortin and Histone H4 expression in endometriosis aligns with this current trend." (PMID 41011062, 2025). "Moreover, women with disorders other than endometriosis also had elevated urocortin levels, but to a lesser extent." (PMID 34201813, 2021). "This, along with heightened urocortin levels in endometriomas, indicates a relationship with the symptoms of endometriosis, and whether that correlation exists between low fertility, inflammation, fibrosis, or spontaneous abortions is still unknown." (PMID 32244319, 2020). "Recently, urocortin (UCN) has been extensively investigatedin the field of endometriosis." (PMID 30644237, 2019). "This is the first time a study shows that CRHR1 and CRHR2 and specifically the CRHR1β and CRHR2α receptor subtypes are expressed at mRNA and protein level, not only in the endometrium but also at endometriotic sites indicating a potential crucial role of CRH and UCN in endometriosis." (PMID 23638035, 2013).
endometriosis (continued). "Despite the fact that CRH/UCN have been implicated in endometriosis – a fact also verified by our results, no data has been reported so far concerning the expression of CRHR1 and CRHR2, the CRH and UCN receptors." (PMID 23638035, 2013). "Some studies have shown that urocortin levels may be altered in individuals with endometriosis." (PMID 39597051, 2024). "We then examined how CRH and UCN regulate galectin-1 expression in an endometrial adenocarcinoma cell line, used as a eutopic epithelial endometrium model, aiming to further elucidate the role of these molecules in eutopic endometrium and infertility problems of women with endometriosis." (PMID 25473847, 2014). "We quantified the mRNA for urocortin and CRH, which are the main agonists of the CRHR1 receptor, within developed endometriosis vesicles in rats from both treatment groups using qRT-PCR." (PMID 30427841, 2018). "We further compared the expression of CRH, UCN, CRHR1 and CRHR2 in ectopic endometrium to that in eutopic endometrium of women with endometriosis." (PMID 23638035, 2013). "In the most investigated group of patients, the levels of UCN-1 were much higher in patients with endometriosis, compared to individuals without specific lesions." (PMID 33946650, 2021). "Interestingly, we found that the expression of CRH, UCN and their receptor subtypes, CRHR1 and CRHR2 is stronger in ectopic endometrium compared to that in eutopic endometrium of women with endometriosis." (PMID 23638035, 2013). "CRH, UCN, CRHR1 and CRHR2 mRNA were also more highly expressed in ectopic rather than eutopic endometrium (CRH, UCN, CRHR2α: p<0.01, CRHR1β: p<0.05) and protein (CRH and UCN: p<0.05, CRHR1 and CRHR2: p<0.01) in women with endometriosis." (PMID 23638035, 2013). "The exact mechanisms and the role of urocortin in endometriosis are not entirely understood." (PMID 39597051, 2024). "Unidentified endometrial defects in endometriosis could also affect the expression of CRH and UCN resulting in increased expression of CRHR1 and CRHR2 acting as a regulatory mechanism to compensate for the reduced efficiency of proper endometrial function of endometriotic women." (PMID 23638035, 2013). "However, the relative expression of CRH, UCN and their receptors in eutopic and ectopic endometrium of endometriotic women and in eutopic endometrium of healthy women and women with endometriosis has never been investigated." (PMID 23638035, 2013). "Immunohistochemistry and western blot analysis were performed in order to identify galectin-1 expression in ectopic and eutopic endometrium of women with and without endometriosis and the regulatory effect of CRH and UCN on galectin-1 expression." (PMID 25473847, 2014). "CRH, UCN, CRHR1 and CRHR2 mRNA were also more highly expressed in ectopic rather than eutopic endometrium in women with endometriosis." (PMID 25473847, 2014).
depression (12 papers, 2013 to 2024). "In male, but not female, suicide victims, UCN mRNA is significantly elevated in the Edinger-Westphal nucleus further implicating a disruption in central CRF-related peptides related to depression." (PMID 24065880, 2013).
colon cancer (6 papers, 2020 to 2024). "Specifically, targeting the UCN gene significantly reduced proliferation in colonic cancer cell lines, underscoring its critical function in modulating the immune landscape of intestinal tumors." (PMID 39336730, 2024). "Perturbation experiments targeting UCN functions in colonic tumor cell lines, Caco-2 and HT-29, significantly inhibited cell proliferation, providing concrete evidence of the tumorigenic mechanisms mediated by UCN." (PMID 39336730, 2024). "Only eight genes (UCN, TRIM, RBCK1, TPM2, CD36, NMB, PPARGC1A, and LGALS4) significantly affected the OS in patients with colon cancer (P < 0.05)." (PMID 35572595, 2022). "We developed and validated a five-immune gene model of colon cancer, including LBP, TFR2, UCN, UTS2, and MC1R." (PMID 32375704, 2020). "In our study, based on the colon cancer immune gene datasets, we used WGCNA to identify 21 immune-related hub genes affecting patients’ OS and constructed IRGPI based on 8 independent OS prognostic factors (UCN, TRIM58, RBCK1, TPM2, CD36, NMB, PPARGC1A, and LGALS4)." (PMID 35572595, 2022).
endometrial cancer (5 papers, 2017 to 2024). Primary or metastatic malignant neoplasm involving the endometrium (mucous membrane that lines the endometrial cavity). "UCN-1, the first UCN discovered, plays a role in endometrial cancer progression, stress-induced gastrointestinal dysfunction, gastrointestinal motor function, and the processing of visceral pain." (PMID 38546882, 2024). "For example, UCN-1 increases the migration of hepatic cancer cells but suppresses the migration ability of endometrial cancer cells." (PMID 38546882, 2024). "UCN is mainly expressed in reproductive organs and urinary systems, and dysregulation of UCN can affect the invasion and metastasis of endometrial cancer." (PMID 35401707, 2022). "UCN-1 affects the migration of hepatic cancer cells and endometrial cancer cells in vitro." (PMID 38546882, 2024). "UCN is a member of the CRH family, and it can inhibit the invasion and metastatic spread of endometrial cancer." (PMID 33330631, 2020).
heart failure (5 papers, 2012 to 2019). Inability of the heart to pump blood at an adequate rate to meet tissue metabolic requirements. "To date, most studies into urocortins have focused on UCN1 and UCN2 in various diseases including heart failure (HF) and have revealed compelling data on the endogenous compensatory role of UCN1 and UCN2 and their cardioprotective effects." (PMID 31781037, 2019).
Obesity (4 papers, 2019 to 2023). Accumulation of substantial excess body fat. "In conclusion, UCN levels are differentially dysregulated in obesity in a tissue-dependent manner and can be mitigated by regular moderate physical exercise." (PMID 31781037, 2019). "Lasting hypermethylation of this region could induce downregulation of UCN expression and a blunted response to its appetite suppressive activity, leading to sustained overfeeding, long-term body weight gain and obesity." (PMID 38093359, 2023). "Moreover, to standardisethe measurement of UCN levels in daily clinicalpractice, further investigation is necessary to determinewhether the peptide concentration is affected by factorsincluding menstrual cycle, obesity, exercise, stress, diabetesmellitus and other chronic diseases." (PMID 30644237, 2019).
Parkinson disease (4 papers, 2007 to 2022). A progressive degenerative disorder of the central nervous system characterized by loss of dopamine producing neurons in the substantia nigra and the presence of Lewy bodies in the substantia nigra and locus coeruleus. "The in vivo results obtained in a Parkinson’s disease mice model showed a neurological recovery, which was associated to the significant transport of urocortin." (PMID 34731414, 2022). "Finally, this brain delivery system was used as a carrier for urocortin (a 40 amino acid long peptide related to corticotropin-releasing factor) which has been found to be neuroprotective and to alleviate the symptoms in a rat model of Parkinson’s disease." (PMID 29425146, 2018). "They found that the OL-PEG-PLGA-URO ENPs were more efficient in the 6-hydroxydopamine (6-OHDA) model of Parkinson’s disease than the PEG-PLGA-URO ones, the latter being more effective than urocortin alone." (PMID 29425146, 2018).
glioma (3 papers, 2023 to 2024). A benign or malignant brain and spinal cord tumor that arises from glial cells (astrocytes, oligodendrocytes, ependymal cells). "However, the increased nuclear intensity especially in less differentiated tumors has been reported before with UCN nuclear positivity being significantly profound in cases of human astrocytomas and gliomas, compared to reactive gliosis." (PMID 37382757, 2024). "Urocortin, CRF, and their receptors have been detected in various human tumors, such as in breast cancer, glioma cell lines, and others." (PMID 36971048, 2023).
Infertility (3 papers, 2013 to 2022). "Eutopic endometrium highly express CRH, CRHR type 1 and 2, as well as urocortin mRNA and protein, thus suggesting that a deranged CRH and Ucn mRNA expression associated with an impaired CRH-R1 activity may affect the process of decidualization and contribute to infertility in these patients." (PMID 34405378, 2022). "Our findings point to a new inflammatory modulator pathway in which CRH, UCN, CRHR1 and CRHR2 are involved acting by an autocrine/paracrine pathway in eutopic and ectopic endometrium potentially affecting the pathogenesis of this benign disease and infertility profile of endometriotic women." (PMID 23638035, 2013).
ischemia (3 papers, 2015 to 2021). A hypoperfusion of the BLOOD through an organ or tissue caused by a PATHOLOGIC CONSTRICTION or obstruction of its BLOOD VESSELS, or an absence of BLOOD CIRCULATION. "In a recent study, urocortin was shown to directly activate AMP-activated protein kinase in ex vivo-perfused mouse hearts and decrease injury and contractile dysfunction during ischemia/reperfusion." (PMID 25667611, 2015).